EGFR (epidermal growth factor receptor)
Diseases named in the same sentence as EGFR in open-access papers (continued):
Sharing a sentence is not in itself a finding about the gene and the disease.
infection (continued). "Accordingly, suppressed neutrophil recruitment and significant mortality in a zebrafish swimbladder model of infection is also observed following EGFR inhibition." (PMID 31127085, 2019). "Our study shows loss of endosomal tubulation when EGFR signaling is blocked, pointing to the role of EGFR signaling both in infection and in virus-induced endosomal tubulation." (PMID 31192164, 2019). "Cells were infected with HPV-16 PsVs and treated with EGFR-specific inhibitor at 6 h post-infection." (PMID 31192164, 2019). "By contrast, the receptor expression of EGFR under the infection of C. albicans SC5314 is higher than C. albicans WO-1." (PMID 30769958, 2019). "During a productive infection, we demonstrate a striking and early downregulation of EGFR from the cell surface and a decrease in total levels." (PMID 31725811, 2019). "The reduced responsiveness of EGR1 to EGF stimulation in infected cells likely reflects diminished EGFR levels and signaling in the context of infection beginning at 24 hpi." (PMID 31725811, 2019). "Similar to HAdV-C2, HAdV-B7 and HAdV-E4 both triggered EGFR autophosphorylation at Tyr1068, and NFκB-p65 phosphorylation at Thr254, within the first hour of infection." (PMID 31425554, 2019). "We measured surface levels of EGFR in fibroblasts infected with the TB40/E strain expressing GFP as a marker for infection, which serves as the parental/wild-type (WT) virus for all studies." (PMID 31725811, 2019). "To further understand the regulation of EGFR during productive infection, we analyzed surface and total levels of EGFR in fibroblasts over a time course of infection from 0–72 hpi." (PMID 31725811, 2019). "In response to pathogen infection, the receptors such as EGFR, ERBB2, CDH1, HSP90B1, and TJAP1 at the host membrane interact with pathogen cell wall proteins to start inducing endocytosis." (PMID 30769958, 2019). "Investigation into the mechanism of EGFR activation during infection revealed the contribution of EGFR ligands, MMPs and calcium flux as key drivers of EGFR signalling and immune stimulation." (PMID 31127085, 2019). "CMV infection blunts EGFR signaling and downstream pathways in productive infection, but EGFR signaling and that of downstream pathways is sustained in CD34+ HPCs." (PMID 31725811, 2019). "In this study, we investigated the role of signaling downstream of EGFR in productive infection in fibroblasts and in latency in CD34+ HPCs." (PMID 31725811, 2019). "As expected, MDA-MB-231 cells infected with the SC sgRNA virus expressed strong EGFR protein, whereas infection with the EGFR sgRNA_2 virus, EGFR protein levels were significantly decreased." (PMID 29849821, 2018). "We observed strong activation of EGFR at 5 and 15 min post infection (p.i.), and therefore selected these time points for our analysis." (PMID 30206219, 2018). "Under mock infection conditions, mTECs expressed EGFR in a diffuse pattern that was predominately near the basolateral surface, and receptor distribution was similar between males and females." (PMID 30012205, 2018). "The result showed that CyD treatment largely increased the EGFR recruitment of ACTN4 during the infection, which suggested that the infection-activated EGFR recruitment of ACTN4 was a direct interaction and independent of actin." (PMID 30687645, 2018). "We also observed similar results in cells undergoing K1 strain RS218 infection, which showed the EGFR-related competitive recruitment of ACTN4 from actin in the cell cytoskeleton." (PMID 30687645, 2018). "We interpret the infection and growth in RS as possibly mediated by a rabbit ortholog of human EGFR." (PMID 29966356, 2018). "The retargeting to EGFR was confirmed by the neutralization of J-EGFR cell infection by the humanized monoclonal antibody cetuximab directed to EGFR." (PMID 29966356, 2018).
infection (continued). "Subsequently, co-immunoprecipitation (Co-IP) experiments were applied to PCN033-infected cell lysates using anti-EGFR antibody, and increased binding of ACTN4 to EGFR was observed during the PCN033 infection." (PMID 30687645, 2018). "This is in sharp contrast to infection in fibroblasts, where EGFR levels are reduced 50–70% compared to uninfected controls, and inhibition of EGFR kinase activity further enhances virus replication." (PMID 30127257, 2018). "While CMV does enter through PDGFR in fibroblasts, endothelial cells, and epithelial cells, little is known about its role in signaling during infection in latency cell types, so focus will be given to EGFR and integrins for this section." (PMID 30127257, 2018). "Previously, we found that phosphoactive EGFR is retained in Rab5- and Rab11a-positive endosomes in infection." (PMID 30042195, 2018). "Within 5 min following entry, infection further alters EGFR-dependent Stat1 signaling to generate pro-survival and motility signals." (PMID 30127257, 2018). "Successful infection of both CD14+ and CD34+ cells has been linked to interactions between the virion and EGFR." (PMID 29547547, 2018). "Consistent with the RNA-seq results, EGFR became phosphorylated upon in vitro infection of human alveolar epithelial cells with several members of the Mucorales, and this phosphorylated, activated form of EGFR colocalized with R. delemar spores." (PMID 30108171, 2018). "To further verify the involvement of ADAM17, we treated the cells with TAPI-1, a specific inhibitor of ADAM17, prior to PCN033 infection, and found that the time-dependent phosphorylation of EGFR induced by PCN033 was completely blocked by TAPI-1." (PMID 30687645, 2018). "Regardless, the EGFR–ErbB3 heterodimerization we observed was essential for the infection-induced EGFR activation as well as for bacterial invasion of the hBMECs because the ErbB3 knock-down significantly delayed and attenuated these phenotypes." (PMID 30687645, 2018). "Together, the body of work demonstrates that CMV manipulates EGFR, integrins, and their downstream pathways for infection, persistence, and dissemination in the host." (PMID 30127257, 2018). "During PCN033 infection, EGFR (Dylight 405 labeled in blue) was recruited and more ACTN4 became bound (shown as the color purple), while contrastingly, the co-location of ACTN4 and F-actin disappeared from view in the cells (arrows indicated)." (PMID 30687645, 2018). "However, whether EGFR-TKIs increase the risk of infections in NSCLC remains unknown." (PMID 28107192, 2017). "Conversely, inhibition of Akt, which is normally activated by the PI3 kinase and itself activates PIKfyve during EGFR endocytosis, leads to an increase in levels of Rab7 on chlamydial endosomes while reducing internalization and infection." (PMID 28787457, 2017). "Remarkably, while the early H. pylori-mediated transactivation of EGFR is independent of CagA, translocated CagA was required for inhibiting EGFR endocytosis and subsequent degradation during prolonged infections." (PMID 28338646, 2017). "In particular, phosphorylation at Y-845, Y-992, Y-1045, and Y-1068 in EGFR was significantly downregulated by Shp2 during prolonged infection." (PMID 28338646, 2017). "This makes these cells susceptible to infection with avian leukosis virus-derived RCAS vectors that carry expression cassettes for e.g., auto-active EGFR variants." (PMID 28074274, 2017). "hBD3 is highly active against H. pylori in vitro and is stimulated by EGFR signaling during early times of infection." (PMID 28338646, 2017). "At day one post-infection, the expression of EGFR and PI3K p85 and p110α subunits were increased in Socs5−/− lungs." (PMID 28195529, 2017). "This suggests that in vivo, SOCS5 regulates PI3K-independent EGFR effects that are required for restraint of the infection." (PMID 28195529, 2017).
infection (continued). "AMP gene expression was abrogated by Helicobacter pylori virulence effectors during prolonged infection via the inactivation of EGFR signaling, to evade a key innate mucosal defense pathway and thus support the establishment of persistent infection." (PMID 28460447, 2017). "There were 18 fatal infections events occurred in the EGFR-TKIs and 21 fatal infections events occurred in control arms, yielding a Peto OR 0.81 (95%CI: 0.43-1.53, p = 0.52)." (PMID 28107192, 2017). "Consistent with this, the expression of the EGFR protein was also much higher in newborn GFP+ ECs than in older GFP- ECs that existed before the infection." (PMID 28485389, 2017). "In conclusion, our data demonstrate that the innate-like effector function of Th2 cells at the site of infection is controlled by EGFR and AREG expression." (PMID 29045902, 2017). "In order to determine the specific contribution of EGFR-TKIs to the development of infections, a meta-analysis of the Peto OR of infections was performed." (PMID 28107192, 2017). "Taken together, these studies implicate EGFR as a major host regulator of infection contributing to CMV persistence in broad contexts of infection." (PMID 27218650, 2016). "Infection of cells with chimeric strains RSV A2-2-20F and A2-2-20GF or over-expression of 2–20 F protein resulted in greater phosphorylation of EGFR than infection with RSV A2 or over-expression of A2 F, respectively." (PMID 27152417, 2016). "In UL135STOP infection, total EGFR levels were 50% (p-value≤0.001) reduced relative to mock-infected cells, but 50% increased relative to WT infection (p-value = 0.0013)." (PMID 27218650, 2016). "We performed similar experiments in serum-starved NCI-H292 (H292) cells, and in an earlier time course we found that A2-2-20F infection resulted in a higher p-EGFR/EGFR ratio than A2 infection at 1, 12, and 24 hr post-infection." (PMID 27152417, 2016). "In the context of HCMV replication, EGFR is transcriptionally downregulated at early times during a productive infection due to the induction of Wilms’ Tumor Factor 1, a known transcriptional repressor of EGFR." (PMID 27218650, 2016). "Using clinically relevant RSV strains and infection models, we found that EGFR is critical for RSV-induced airway mucin expression and laid the groundwork for defining the molecular interaction between F and EGFR." (PMID 27152417, 2016). "By using genotype 1b replicon cells as well as an infection-based system we found that while transcript and protein levels of EGFR and ErbB2 were up-regulated or unaffected, respectively, HCV induced a substantial reduction of ErbB3 and ErbB4 expression." (PMID 26886748, 2016). "These experiments indicate that both pUL135 and pUL138 interact with EGFR when expressed alone and in the context of infection." (PMID 27218650, 2016). "Subsequently, the phosphorylation of EGFR upon infection was investigated through immunoprecipitation with anti-EGFR antibody." (PMID 27756321, 2016). "For example, Pseudomonas aeruginosa and H. pylori were shown to induce transactivation of EGFR to prevent epithelial cell apoptosis during the early stage of infection, thereby facilitating their survival in the host cells." (PMID 27711202, 2016). "We examined total cellular levels of EGFR in the context of infection with WT, UL135STOP or UL138STOP." (PMID 27218650, 2016). "As previous studies have supported the association of SS2 infection with a strong inflammatory response in vivo, we then investigated if EGFR participated in the neuroinflammatory process in response to SC19 infection." (PMID 27756321, 2016). "We investigated for the first time the tyrosine phosphorylation of cellular proteins in response to SS2 strain SC19 infection of hBMEC and demonstrated the contribution of EGFR to SS2-induced neuroinflammation." (PMID 27756321, 2016). "The kinetics of EGFR trafficking back to the surface during UL135STOP infection exceeded the kinetics observed in uninfected cells (60 vs. 90 min)." (PMID 27218650, 2016).
infection (continued). "In contrast, EGFR inhibition prior to A2-2-20F or A2-2-20GF infection at MOI = 3 reduced infection efficiency." (PMID 27152417, 2016). "Our results demonstrate that RSV F interacts with EGFR in a strain-specific manner, EGFR is a co-factor for infection, and EGFR plays a role in RSV-induced mucin expression, suggesting EGFR is a potential target for RSV disease." (PMID 27152417, 2016). "Inhibition of EGFR in WT infection resulted in a 3-fold and 6-fold greater frequencies of infectious centers produced prior to reactivation and following reactivation, respectively." (PMID 27218650, 2016). "The internalization of EGFR following EGF stimulation in UL135STOP infection reflected that of WT infection at the early time points, marked by early oscillation in EGFR surface levels." (PMID 27218650, 2016). "In HeLa cells, activation of epidermal growth factor receptor (EGFR) is a necessary step in infection." (PMID 27014223, 2016). "In contrast to infection in fibroblasts, EGFR surface levels were increased 1 dpi in WT-infected CD34+ HPCs relative to uninfected CD34+ HPCs." (PMID 27218650, 2016). "UL135STOP infection resulted in increased levels of EGFR relative to WT infection, consistent with our findings in fibroblasts." (PMID 27218650, 2016). "EGFR inhibition abrogated 2–20 F-mediated infection in vitro and mucin expression induction in vivo." (PMID 27152417, 2016). "Western blotting was performed to determine levels of total EGFR and phospho-EGFR (p-EGFR) after infection of HEp-2 cells with RSV strains A2 and A2-2-20F." (PMID 27152417, 2016). "As such, EGFR represents a potentially powerful target for viral manipulation during infection with complex DNA viruses." (PMID 27218650, 2016). "The infection behavior of pilTL201C is also defective, due to its inability to activate the EGFR-heparin-binding EGF-like growth factor (HB-EGF) pathway." (PMID 27923924, 2016). "Due to the altered trafficking and activation of EGFR, we analyzed the subcellular distribution of EGFR in the context of infection." (PMID 27218650, 2016). "The differences in EGFR trafficking are summarized by plotting EGFR surface levels (relative to levels prior to EGF stimulation in each infection) at 1, 10, 25 and 60 minutes." (PMID 27218650, 2016). "We show that activated EGFR is sequestered within the infection-induced, juxtanuclear viral assembly compartment and is unresponsive to stress." (PMID 27218650, 2016). "We report that RSV F interacts with and activates EGFR and that EGFR contributes to infection in vitro and plays a critical role in RSV-induced mucin expression." (PMID 27152417, 2016). "The infection behavior of pilTL201C is also defective, due to its failure to activate the epidermal growth factor receptor (EGFR)-heparin-binding EGF-like growth factor (HB-EGF) pathway." (PMID 27923924, 2016). "This suggests that pUL135 alone stimulates reduction of EGFR levels at the cell surface, whereas pUL138 requires additional viral or infection-induced factors to stimulate EGFR expression at the cell surface." (PMID 27218650, 2016). "The full extent of the EGFR signaling programs induced by Tfp retraction and their consequences for infection remain to be investigated." (PMID 27923924, 2016). "The coincidence of Rab 5 or Rab 11 with cytosolic EGFR has a Pearson correlation of 0.1 in uninfected cells, which rose to ≥0.3 in all infection conditions analyzed." (PMID 27218650, 2016). "Our current working model is that initial 2–20 G interactions with CX3CR1, GAGs, and/or other factors mediates attachment that likely precedes F-EGFR interaction, EGFR activation, and infection." (PMID 27152417, 2016). "Prior to the EGF pulse, EGFR surface levels were increased or decreased in UL135STOP or UL138STOP infection relative to that of WT-infected cells, as anticipated from our analysis of surface levels." (PMID 27218650, 2016).
infection (continued). "Because pUL138 has been shown to alter MRP-1 and TNFR at the cell surface, we wanted to determine if EGFR surface levels were altered during infection." (PMID 27218650, 2016). "The results showed that the pattern of increased SphK2 phosphorylation upon infection with meningitic E. coli was similar between HBMEC expressing dominant-negative EGFR and HBMEC expressing the control vector." (PMID 27711202, 2016). "A2-2-20F-infected cells had a higher ratio of p-EGFR to EGFR than A2-infected cells at 24 h post-infection." (PMID 27152417, 2016). "The infection defect of pilTL201C and ΔpilT cells is due to their inability to signal through the EGFR pathway." (PMID 27923924, 2016). "The virus activates EGFR when it infects monocytes, and employs integrins and paxillin at the beginning of infection." (PMID 26147640, 2015). "In this study, the persistent elevated expression of EGFR observed in chronically infected mice exposed to METH compared to infection alone is worth noting." (PMID 26322025, 2015). "While blocking EGFR inhibits infection of HaCaT cells with both HPV16 PsV, HPV31 PsV and HPV31 QV, the actual role for EGFR has yet to be determined." (PMID 26247955, 2015). "We demonstrate that during infection signaling through EGFR activates a p38 MAPK signaling pathway that prevents macrophages from effectively responding to infection." (PMID 24586159, 2014). "Depletion of the receptor in HEp-2 cells by specific siRNA, addition of EGF or blocking of the ligand-binding pocket with an anti-EGFR antibody significantly reduced both EB attachment and infection." (PMID 23633955, 2013). "The respiratory epithelium is subject to continuous environmental stress and its responses to injury or infection are largely mediated by transactivation of the epidermal growth factor receptor (EGFR) and downstream signaling cascades." (PMID 23349873, 2013). "These downregulated miRNAs can upregulate EGFR expression, resulting in easier virus replication and propagation at the early stage of infection." (PMID 23731466, 2013). "The accumulation of active EGFR around the inclusion containing endocytosed EBs 60 min post infection, points to a role for (active) EGFR beyond the entry process per se." (PMID 23633955, 2013). "Inhibition of PI3K (wortmannin, Ly294002, PI-103), a downstream effector of EGFR, also reduced infection." (PMID 23593008, 2013). "The EGFR/Pmp21 interaction data and colocalization of EGFR with EBs in endocytic vesicles imply an important function for EGFR in the initiation of infection." (PMID 23633955, 2013). "While EGFR is a central mediator of Akt activation in the early stages after T. gondii, Akt phosphorylation has recently been reported at 24 h post-infection with the parasite." (PMID 24367261, 2013). "Infection levels measured 24 h later were reduced in a dose-dependent manner that closely paralleled the level of EGFR knockdown." (PMID 22346752, 2012). "For example, EGFR signaling is known to be activated during infection by respiratory viruses FLU and ENTERO." (PMID 22432004, 2012). "Next, we aimed to investigate if infection activates FAK autophosphorylation and if this is associated with the activation of EGFR and PDGFR receptors, which are also present in membrane lipid rafts." (PMID 22204307, 2011). "Altogether, these results indicate that the EGFR pathway is both required and sufficient in ISCs to promote their proliferation in response to infection." (PMID 21176204, 2010). "Immunofluorescence data showed internalized EGFR in infections with VacA-expressing Hp,providing a possible mechanism for how significant portions of EGFR are inactivated by VacA." (PMID 22069547, 2010). "Several members of the EGFR pathway are induced at the transcriptional level in the gut upon Ecc15 infection." (PMID 21176204, 2010). "We first investigated the role of the EGFR pathway in epithelial delamination by analyzing the dynamics of adherens junction in the gut during infection." (PMID 21176204, 2010).